ANG (angiogenin)
Diseases named in the same sentence as ANG in open-access papers (continued):
Sharing a sentence is not in itself a finding about the gene and the disease.
breast carcinoma (27 papers, 2004 to 2026). "It has been established that angiogenin is associated with increased production of tRNAHisGTG in breast cancer cells." (PMID 30023000, 2018). "DEC1 is induced by hypoxia through a HRE, and in our study we have demonstrated a significant association with HIF-1α and the hypoxia-induced gene angiogenin, supporting its induction by this microenvironmental stress in breast cancer." (PMID 15328513, 2004). "The role of ANG in cell migration, necessary for tumour invasion and metastasis, has been confirmed by an important study which detected elevated levels of secreted and cell surface-bound ANG in highly invasive metastatic breast cancer cells." (PMID 31500197, 2019). "Angiogenin is usually upregulated in various cancers such as colorectal carcinoma, breast cancer, and HCC, and it promotes angiogenesis and induces cancer proliferation." (PMID 27502492, 2016). "In breast cancer, increased angiogenin expression promotes the transition from normal to invasive breast carcinoma." (PMID 24424657, 2014). "In this study, we further investigated the regulatory role of ANG in ERRγ expression in breast cancer cells." (PMID 23977052, 2013). "In addition, the expression of ANG has been shown to be significantly increased in breast cancer tissue, which was also marked as a favorable prognostic marker in primary breast carcinoma." (PMID 34513302, 2021). "Given our observation that ANG negatively regulates ERRγ expression, we proposed that ERRγ might be involved in ANG-regulated proliferation of breast cancer cells." (PMID 23977052, 2013). "In the current study, XAN, BER, ANG, PSO, IMP were selected on the basis of their best docking scores against breast cancer which was further validated by specific in-vitro assays of ERα, EGFR and mTOR." (PMID 31673107, 2019). "We have recently shown that angiogenin is estrogen regulated in a similar fashion as VEGF in normal breast tissue and experimental breast cancer." (PMID 21984941, 2011). "ANG was identified by both LASSO and Random Forest; its expression increases under low oxygen conditions, aiding in angiogenesis and tumor survival, with studies showing that its inhibition can reduce breast cancer growth in vivo." (PMID 41017855, 2025). "In studies of ER+ breast cancer, researchers have discovered that sex hormones and their receptors regulate SHOT-RNA production by activating ANG to cleave aminoacylated mature tRNA, and the accumulation of the resulting SHOT-RNA contributes to breast cancer cell proliferation and tumorigenesis." (PMID 38577588, 2024). "The research has also illustrated that MBP-1 suppresses the activity of endothelin-1 (ET-1), angiogenin (ANG), interleukin-8 (IL-8), MMP-9, placental growth factor (PGF) and vascular endothelial growth factor (VEGF), which all accelerate cell apoptosis in breast cancer cells (MCF-7)." (PMID 30518090, 2018). "Indeed, transient knockdown of ZNF121 significantly promoted the expression of ANG in both the T‐47D breast cancer cell line and the MCF10A non‐neoplastic human breast epithelial cell line." (PMID 30524945, 2018). "Another type of tsRNAs, called sex hormone-dependent tRNA-derived RNAs (SHOT-RNAs), are produced by sex hormone-induced angiogenin (ANG, known as RNY1 in yeast) cleavage of fully acylated mature tRNAs and are abundantly expressed in breast cancer (BC) and prostate cancer (PC)." (PMID 37692525, 2024).
heart failure (22 papers, 2012 to 2024). Inability of the heart to pump blood at an adequate rate to meet tissue metabolic requirements. "Downregulated miR-199 also increased levels of atherosclerosis-related biomarkers (Angiogenin, Galactin-3 and Neuropilin-1) in heart failure patients with peripheral artery disease." (PMID 36071532, 2022). "A clinical study collected serum from 16 patients with heart failure with preserved ejection fraction (HFpEF) and 16 healthy individuals, and found that ANG differed the most among 507 proteins between the two groups." (PMID 33041815, 2020). "ANG is a major inducer of tRNA halves, and several studies suggest ANG is involved in cardiac hypertrophy and heart failure." (PMID 33041815, 2020). "Significantly increased Angiogenin expression has been correlated with many pathological conditions and disease severities like heart failure, pathogenesis of myocardial ischemia and diabetic retinopathy." (PMID 24303036, 2013). "Interestingly, ANG has been proposed to be a biomarker for left ventricular systolic dysfunction and heart failure." (PMID 33041815, 2020). "Moreover, patients with heart failure, the typical end stage of most CVDs, presented with increased serum ANG levels compared with healthy controls, according to the results of the pooled analysis (pooled SMD = 0.812, 95% CI = 0.592 to 1.032, p < 0.001)." (PMID 29736193, 2018). "The serum ANG concentrations were significantly higher in patients who developed colorectal cancer, acute myeloid leukemia, multiple myeloma, myelodysplastic syndromes, and heart failure than those in healthy controls." (PMID 29736193, 2018). "The serum ANG concentrations were significantly elevated in patients who developed colorectal cancer, acute myeloid leukemia, multiple myeloma, myelodysplastic syndromes, and heart failure." (PMID 29736193, 2018). "All patients we enrolled were in stable phase coronary heart disease, and our results were in agreement with other studies where ANG might be a biomarker for heart failure." (PMID 27872509, 2016). "However, the serum ANG levels were significantly elevated in patients with heart failure, the terminal stage of most CVDs, compared with those in healthy controls, which may explain the changes in angiogenic activity noted in affected patients." (PMID 29736193, 2018). "Plasma angiogenin levels were elevated in patients with coronary artery disease, acute coronary syndrome (ACS) and heart failure with preserved ejection fraction." (PMID 38360721, 2024). "In addition, higher angiogenin levels were also predictive of adverse events (composite of cardiovascular death, recurrent ACS, revascularization and heart failure) in the short term (6 months) in patients with ACS." (PMID 38360721, 2024). "Therefore, it is likely that dysregulation of ANG in cardiac hypertrophy, heart failure, and other cardiovascular diseases may lead to tsRNA dysregulation in the heart, and it is worth further investigating the potential biological function of ANG-induced tsRNAs in these instances." (PMID 33041815, 2020).
Obesity (20 papers, 2012 to 2025). Accumulation of substantial excess body fat. "Angiogenic factors, including angiogenin, were associated with adipose tissue remodelling and development of obesity." (PMID 38483771, 2024). "Paternal inflammation-induced metabolic abnormalities in children are linked to ANG-mediated synthesis of 5'-tsRNAs in sperm, and offspring of inflamed fathers have metabolic diseases such as glucose intolerance and obesity." (PMID 35677823, 2022). "Obesity was also associated with increased expressions of angiogenesis-related proteins, in particular, angiogenin, endoglin, endostatin, endothelin-1, IGFBP-3, leptin, MMP-3, PAI-1, TIMP-4, CXCL16, platelet factor 4, DPPIV and coagulation factor III." (PMID 22748184, 2012). "Integrating previous reports and bioinformatics analysis, we hypothesized that ANG expression is associated with obesity and involved in EC progression by affecting tumor angiogenesis." (PMID 36761027, 2023). "OB-derived angiogenin — another factor elevated in obesity — can promote HSC quiescence, as loss of angiogenin from osteolineage BM cells leads to increased proliferation of the HSC pool." (PMID 33554957, 2021). "As previous studies suggested that production of certain cytokines can be affected by age, obesity and serum lipids we aimed to verify if these factors affect also endostatin, VEGF, IL-8, angiogenin and bFGF measured in our study." (PMID 25951297, 2015). "It was suggested previously that serum lipids and obesity may change concentration of several cytokines, therefore we aimed to verify if endostatin, VEGF, IL-8, angiogenin and bFGF are affected by these factors in our patients." (PMID 25951297, 2015).
Parkinson disease (20 papers, 2012 to 2025). A progressive degenerative disorder of the central nervous system characterized by loss of dopamine producing neurons in the substantia nigra and the presence of Lewy bodies in the substantia nigra and locus coeruleus. "For example, ANG variants have also been identified in familial Parkinson’s disease (PD) patients from Germany, the Netherlands, and Italy." (PMID 38421827, 2024). "Parkinsonism has been noted in kindreds with ANG mutations and variants in the ANG gene have been found to associate with PD in two Caucasian populations." (PMID 25386690, 2014). "More recently, a link between angiogenin mutations and Parkinson’s disease has also been demonstrated." (PMID 23181008, 2012). "Both ALS and Parkinson's Disease (PD) are associated with mutations in the angiogenin gene." (PMID 32890397, 2020). "In addition, some ALS patients harboring ANG variants also showed signs of Parkinson disease, presenting a genetic link of hRNase5/ANG between ALS and Parkinson disease." (PMID 30449278, 2018). "Moreover, a relationship between mutations in the ANG gene and Parkinson’s disease has been revealed." (PMID 26213621, 2015). "Notably, studies have shown that several ALS patients carrying ANG mutations also demonstrated signs of Parkinsonism." (PMID 25386690, 2014). "Angiogenin is frequently mutated in ALS and Parkinson's disease, which would suggest that the abundance of 5 ́-tRNA halves decreases uniformly in ALS." (PMID 39982687, 2025). "Mutations in ANG (angiogenin) have been found to segregate with both familial and sporadic forms of ALS and Parkinson’s disease." (PMID 26578880, 2015). "Moreover, parkinsonism can be involved in cases with TDP-43, ANG, OPTN, and CHMP2B mutations." (PMID 26213621, 2015). "Notwithstanding the cumulative evidence gathered thus far, the role of angiogenin in the physiology and pathophysiology of the nervous system, in particular ALS and Parkinson’s disease, requires further investigation." (PMID 23181008, 2012).
Stroke (20 papers, 2013 to 2025). Sudden impairment of blood flow to a part of the brain due to occlusion or rupture of an artery to the brain. "ANG expression has been identified also in neurons and acts as a part of the secretome of endothelial progenitor cells (EPCs); the modulation of ANG and EPCs as repair-associated factors has been found in stroke patients and mouse models of rehabilitation after cerebral ischemia." (PMID 31500197, 2019). "Our results position angiogenin in the neurogenic SVZ during stroke recovery, suggesting potential therapeutic interventions in neurorepair beyond the known actions on angiogenesis." (PMID 34234733, 2021). "Our recent work also in serum ANG reported that blood ANG was increased in stroke patients after IRT, which is being confirmed in the present study with a larger cohort." (PMID 34899582, 2021). "Serum ANG levels were first reported higher in patients with stroke within 48 h and on days 3 and 7, but decreasing at 14 days compared to control subjects, but the rehabilitation interventions were not described in this work." (PMID 34899582, 2021). "More brain angiogenin content was found during the acute phase of stroke in infarct tissue compared to the contralateral hemisphere (mean fold increase of 6.5), although differences were not significant." (PMID 30008694, 2018). "Our results describe for the first time an increase of angiogenin and EPCs levels during rehabilitation therapy after stroke." (PMID 30008694, 2018). "As observed in human stroke samples, angiogenin was found in the mouse brain after cerebral ischemia and was increased in the ipsilateral cortex and more specifically in neurons." (PMID 30008694, 2018). "The elevated transcript levels of angiogenin and angiopoietin-1 observed after surgery imply that administering virgin coconut oil could yield neuroprotective benefits post-stroke." (PMID 40649993, 2025). "In this regard, we focused on angiogenin (ANG), a member of the ribonuclease superfamily that acts as a potent angiogenic protein triggering cell proliferation, migration, or survival, which has been recently identified as a repair-associated factor in post-stroke rehabilitation by our group." (PMID 34899582, 2021). "It has been determined that the levels of plasma angiogenin and angiopoietin after an incidence of ischemic stroke are low, and it has been attributed to poor outcomes, and interventions that may upregulate its expression can potentially improve stroke outcomes." (PMID 40649993, 2025). "Previous studies demonstrated that treatment with BMSCs alone significantly increased the expression of angiogenin, MMP9 and ED‐1 in T1DM stroke rats, leading to the failure of BMSCs treatment against stroke." (PMID 34622573, 2021). "The present investigation focuses on describing angiogenin expression in the adult SVZ and its putative effects on neurogenic responses after stroke." (PMID 34234733, 2021). "In the present study, we focused on two well-known angiogenesis mediators: a molecular player (angiogenin) and a cellular source which sustains angio-vasculogenesis (endothelial progenitor cells, EPCs); both with unknown role as responders to rehabilitation therapy after stroke." (PMID 30008694, 2018). "In conclusion, we have described for the first time the modulation of angiogenin and EPCs in stroke patients under IRT and in a mouse model of post-stroke rehabilitation task-oriented exercise." (PMID 30008694, 2018). "We found that combination treatment of stroke in T1DM rats significantly decreased MMP9 and Angiogenin expression compared to BMSC monotherapy or T1DM-control groups." (PMID 24303036, 2013). "Moreover, thrombin preconditioning of MSCs remarkably enriched their cargo contents, such as angiogenin, hepatocyte growth factor, vascular endothelial growth factor and BDNF, which are known to alleviate brain damage after stroke, compared to naïve MSCs." (PMID 35457266, 2022).
Stroke (continued). "It is important to remark that the main limitation of our study is that we have not included a control cohort of stroke patients of similar characteristics who did not receive IRT to truly elucidate the role of rehabilitation in the modulation of angiogenin and EPCs." (PMID 30008694, 2018).
atherosclerosis (16 papers, 2010 to 2024). A disease characterized by the build-up of fatty material and calcium deposition in the arterial wall resulting in partial or complete occlusion of the arterial lumen. "Therefore, our results indicate that the endothelium might contribute to accelerated atherosclerosis in uremic conditions by upregulating angiogenin expression." (PMID 33574979, 2021). "Therefore, abnormal inactivation of VEGF and angiogenin expression may exert a pivotal function in the occurrence and development of atherosclerosis." (PMID 31487691, 2019). "The fact that only nine proteins were differentially expressedbetween CVDI and CVDII patients, and among them only angiogenin was associated witheGFR highlights the notion that the majority of lipid metabolism proteins arealtered due to atherosclerosis, not kidney dysfunction." (PMID 27600335, 2016).
prostate carcinoma (16 papers, 2013 to 2023). A carcinoma that arises from epithelial cells of the prostate gland. "Angiogenin expression has been associated with STAT3 signalling in prostate cancer and with HIF-1α in oral cancer." (PMID 37896150, 2023). "In prostate cancer, plexin-B2 plays a role together with angiogenin in the regulation of the stemness of prostate cancer stem cells (CSC)." (PMID 37627074, 2023). "We therefore also measured ANG levels in the plasma of this cohort of patients and found that plasma ANG amount was 475.1 ± 8.6 ng/ml in prostate cancer patients, higher than that in control subjects (379.3 ± 6.3 ng/ml, p < 0.0001)." (PMID 35752711, 2022). "ANG is another member of the pancreatic RNase superfamily and has been shown to promote prostate cancer progression and to be co-regulated and co-expressed with RNASE432,33." (PMID 35752711, 2022). "ROC curve analysis of ANG showed an AUC of 0.79 at the 394 ng/ml optimal cut-off value, confirming that it is a good diagnosis marker for prostate cancer, but RNASE4 was better with a higher AUC value (0.94)." (PMID 35752711, 2022). "We found that ANG is mainly located in stress granules of CSCs and in the nucleolus of differentiated prostate cancer cells." (PMID 31942000, 2020). "Monoclonal antibodies of angiogenin and plexin-B2 sensitize prostate cancer stem cells to chemotherapy, highlighting the targeting potential of this regulation." (PMID 31942000, 2020). "The anti-prostate cancer activity of ANG mAb 26-2F has been well documented and has served as proof-of-concept that inhibition of ANG activity would be an effective means for cancer therapy." (PMID 31942000, 2020). "In breast and prostate cancer, specific tRNAs, such as cytoplasmic tRNALys and tRNAHis, are cleaved by angiogenin, and the tRNA half fragments are abundantly expressed in a sex hormone-dependent manner." (PMID 30127802, 2018). "We found that angiogenin knockdown in prostate cancer cells reduced the expression of tRF-315." (PMID 33406670, 2021). "Prostate cancer cell (PC-3) is another reported target cell line for both ANG and ERRγ." (PMID 23977052, 2013). "Angiogenin upregulation is not restricted to ccRCC and has been described in other cancer types, such as breast, pancreatic, colorectal, and prostate cancers." (PMID 38025776, 2023). "We confirmed that tRF-315 derived from tRNALys does not affect the proliferation of prostate cancer cells, including LNCaP cells, but it was indirectly confirmed that tRF-315 could be generated by the activity of angiogenin." (PMID 33406670, 2021).
endothelial dysfunction (15 papers, 2009 to 2025). In vascular diseases, endothelial dysfunction is a systemic pathological state of the endothelium (the inner lining of blood vessels) and can be broadly defined as an imbalance between vasodilating and vasoconstricting substances produced by (or acting on) the endothelium. "In migraine patients during interictal period, depletion of VEGF and angiogenin, two cooperating proangiogenic factors, can be responsible for endothelial dysfunction and increased risk for vascular disorders." (PMID 28918499, 2017). "In conclusion, depletion of VEGF and angiogenin, two closely related proangiogenic regulators, in migraine patients during interictal period creates a milieu of factors that can be responsible for endothelial dysfunction and increased risk of vascular disorders." (PMID 28918499, 2017). "Angiogenin plays a significant role in the pathogenesis of endothelial dysfunction." (PMID 37761032, 2023). "Thus, low angiogenin concentration may aggravate the effects of decreased VEGF on endothelial dysfunction in our patients." (PMID 28918499, 2017).